TXNIP (thioredoxin interacting protein)
Diseases named in the same sentence as TXNIP in open-access papers (continued):
Sharing a sentence is not in itself a finding about the gene and the disease.
tumor (continued). "Irrespectively of positive or negative cytoplasmic expression in tumour cells TXNIP showed a strong expression in endothelial cells of the tumour stroma." (PMID 34433833, 2021). "Informative data was also obtained from 369 HCC samples and 51 non-tumor samples collected from The Cancer Genome Atlas (TCGA), where the downregulation of TXNIP was observed in HCC samples compared to non-tumor samples." (PMID 33323975, 2021). "To establish the role of TXNIP and downstream genes HIF1α and IL1β in the biology of cRCC, we have applied immunohistochemistry to multi-tissue arrays containing tumours of 691 patients without detectable metastases at the time of operation." (PMID 34433833, 2021). "Therefore, further investigations on TXNIP expression on the tissue protein level may be useful to determine whether TXNIP can constitute different subsets of patients and might be a prognostic marker and to further delineate its role as a possible tumor suppressor." (PMID 33081035, 2020). "Importantly, in parallel to changes in DNA and histone H3 methylation status, we found a marked re-expression of methylation-regulated tumor suppressor genes: CDK2NB, KLF4, ID4, and TXNIP." (PMID 32138178, 2020). "While the (human) tumor cells lacked any TXNIP expression, murine TXNIP expression was absent in intra- and peri-tumoral leukocytes but became gradually positive in leukocytes residing in the outer margins of the surrounding connective tissues." (PMID 33081035, 2020). "Intriguingly, TXNIP expression became gradually lower in the proximity of the primary tumor tissue and was absent in leukocytes directly adjacent to tumor tissue." (PMID 33081035, 2020). "The percentage of tumor samples with TXNIP positive versus negative leukocytes in the connective tissues was assessed." (PMID 33081035, 2020). "Inhibition of glucose uptake and activation of apoptosis via reactive oxygen species have been reported as the main mechanisms of tumor suppression by TXNIP; however, the unified molecular mechanism has not been clarified." (PMID 32511893, 2020). "We identified seven oncogenes (NRAS, EGFR, RXRA, HRAS, KRAS, AKT1, ERBB2; q<0.10) and seven putative tumor suppressor genes (ARID1A, TXNIP, CTNNB1, PIK3RI, CDKN2A, KLF5, STAG2; q<0.10) significantly regulated between tumor and control, which were formerly reported to be altered in BC." (PMID 30419021, 2018). "Our results show that TXNIP expression is significantly increased in HCC compared to non-tumor counterparts (p < 0.0001) as well as to normal (p < 0.0001) and cirrhotic (p < 0.0001) liver tissues." (PMID 30627326, 2018). "TXNIP, also known as Vitamin D3 up-regulated protein 1 (VDUP-1) or thioredoxin binding protein 2 (TBP-2), is a key regulator of the redox system, and has been identified as a tumor suppressor." (PMID 28029659, 2017). "Tumor suppressors, MX1 and TXNIP, were proven to be direct targets of the miRs." (PMID 27121770, 2016). "Though there was a significant attenuation in bioluminescence as well as a trend toward smaller tumors with the TXNIP-expressing HTh74 cells compared to vector controls, the final tumor volumes were not significantly different (data not shown)." (PMID 24645981, 2014). "TXNIP, TUSC2, PPFIBP2, GALNT10 and MAP2K3 demonstrated varying degrees of methylation on their promoter regions in normal mucosa, normal salivary rinses and HNSCC tumor samples respectively." (PMID 23403885, 2013). "Each clinically detected tumour in ESRD/ACRD kidney is accompanied by multiplex pre-neoplastic lesions showing similar histological pattern, which may explain the field effect of imbalance of TXNIP/TXN redox system and elevated ROS." (PMID 39020292, 2024).
tumor (continued). "For example, tumor-promoting miRNA-27a-3p and miRNA-660-5p loaded in M2-sEVs lead to the overexpression of these in HCC cells, respectively, downregulating thioredoxin-interacting protein (TXNIP) and Krüppel-like factor 3 (KLF3) that can inhibit tumor development." (PMID 35832790, 2022). "Interestingly, high expression of the TXNIP gene was related to poor OS prognosis for OV and STAD (all P < 0.05), suggesting the prognostic value of TXNIP may has tissue or tumor specificity." (PMID 35843949, 2022). "The Warburg effect especially holds true for cancer cells grown in vitro, which might explain absent TXNIP expression in almost all tumor cell lines and all xenograft tumors." (PMID 33081035, 2020). "Moreover, the results question the role/importance of TXNIP in mediating 1,25(OH)2D3’s anti-cancer effects since in cell lines where TXNIP levels are reduced by 1,25(OH)2D3, such as LNCaP and MCF-7, treatment has been shown to induce profound anti-tumor actions." (PMID 29534438, 2018). "Although TXNIP is known as a tumor suppressor, it has not been applied in any cancer therapy yet." (PMID 30410860, 2018). "In addition, among the adjacent non-tumor liver tissues tested, 31 out of 66 (47.0%) adjacent cirrhotic liver tissues and 1 out of 7 (14.3%) non-cirrhotic liver tissues expressed TXNIP." (PMID 30627326, 2018). "Although bioluminescence signals were attenuated in the TXNIP-expressing HTh74 cells versus controls, final tumor volumes were not significantly different, though a trend toward smaller tumors with injection of the TXNIP-expressing HTh74 cells compared to vector controls was observed." (PMID 24645981, 2014). "In particular, TXNIP depletion could be of interest in combination with immunotherapies (such as anti-PD-1 or other immune checkpoint blockers) to boost T cell immunity and/or for the development of next-generation CAR-T cells by improving their anti-tumor efficacy." (PMID 40260243, 2025). "However, Dpep also kills tumor cells in which TXNIP is not upregulated." (PMID 38920655, 2024). "Furthermore, it has been shown that PCA has significantly increased RNF2 expression and that RNF2 inhibition can increase TXNIP expression by binding to the TXNIP promoter, which may result in PCA cell-cycle arrest, enhancing apoptosis and preventing tumor progression." (PMID 36366411, 2022). "However, the role of TXNIP in tumor invasion and metastasis has not yet been addressed in HCC." (PMID 30627326, 2018). "It is remarkable the increase of TXNIP in mice that successfully responded to ADT compared to non-responders and primary tumor." (PMID 41213907, 2025). "Subsequently, T cell killing in response to HLA-A2+ A375 tumor cells presenting NY-ESO-1 was compared between NT (non-transduced), NY WT (TCR only) and NY KO (TCR with TXNIP KO) T cells." (PMID 40260243, 2025). "In summary, our data suggested that Ct-HBx downregulated the expression of TXNIP by transactivation through the transcription repressor NFATC2, then TXNIP exerted its tumor-suppressing function in HBV-induced HCC by negative regulating glycolytic metabolism." (PMID 33323975, 2021). "In line with a potentially more “silenced” phenotype, these nonlesional tumor cells harbored elevated levels of CXCR4, CD69, HSPA1A, ZFP36, IL7R and TXNIP when compared to matched lesional skin." (PMID 34583709, 2021). "Therefore, it is possible that the 1,25(OH)2D3 regulation of TXNIP, and subsequently glucose uptake, is subject to regulation of upstream pathways by treatment, and that the “canonical” induction in TXNIP expression by 1,25(OH)2D3 may not be observed in different tumor types." (PMID 29048387, 2017). "Furthermore, DTC cell lines and primary PTC tumors have high endogenous TXNIP levels, whereas TXNIP expression is low or absent in ATC cell lines and primary tumor specimens." (PMID 24645981, 2014).
tumor (continued). "Immunohistochemical results suggested that in tumor tissues, CASP8 and SAMSN1 showed high staining, TXNIP showed medium staining, while KLF6 and XCL1 showed negative staining; in normal tissues, KLF6 showed medium staining, CASP8 and SAMSN1 showed low staining, while TXNIP showed negative staining." (PMID 40149637, 2025).
cancer (177 papers, 2007 to 2026). A tumor composed of atypical neoplastic, often pleomorphic cells that invade other tissues. "An imbalance of SELENOM can have deleterious effects, but what is more apparent is that SELENOM strikes a balance with its binding partners such as TXNIP; too much can cause increased cell growth and cancers, too little can cause neurodegenerative diseases." (PMID 38001759, 2023). "Consistent with a role in restricting cell growth, TXNIP expression is suppressed by multiple cancer-associated progrowth signaling pathways, and its expression is typically low in tumors compared to adjacent normal tissue." (PMID 36930677, 2023). "Hyaluronic acid degradation causes a reduction in thioredoxin-interacting protein (TXNIP) levels in cancer cells." (PMID 36769044, 2023). "Given TXNIP’s central role, its loss being a positive for cancer survival is prima face contradictory, however, the key here is perhaps TXNIP’s impact on its environment." (PMID 37794178, 2023). "Metabolic reprogramming is a hallmark of cancer development and metastasis and TXNIP-dependent metabolic phenotypes are associated with patient prognosis." (PMID 37794178, 2023). "Unraveling the overall situation of the expression, mutation, immune response and prognostic potential of TXNIP is of great significance to grasp its essential role in cancer." (PMID 35843949, 2022). "The risk of cancer development is high in TXNIP-deficient mice, which should be considered when knocking out TXNIP in bone research." (PMID 36059548, 2022). "Reportedly, in BC, TXNIP is down-regulated in cancer cells according to grade and stage, and loss of TXNIP expression promotes BC progression." (PMID 35743212, 2022). "While the last few years have provided considerable knowledge of TXNIP roles in the regulation of energy metabolism and associated pathologies, less is known regarding TXNIP contribution to the development of cancers." (PMID 33846376, 2021). "TXNIP appears to be at the crossroads of various signaling molecules implicated in tumorigenesis and anti-cancer treatment, such as Myc, AMPK, and mTOR, making its regulation subject to diverse cellular processes." (PMID 29534438, 2018). "Co-treatment of lentinan with paclitaxel, an anti-cancer drug, to A549 cells induces reactive oxygen species (ROS) production and thioredoxin-interacting protein (TXNIP) expression, which are tightly associated with NLRP3 inflammasome activation." (PMID 28465544, 2017). "It has been reported before that increased expression of TXNIP underlies the differential effect of vorinostat on cancer cells." (PMID 27196668, 2016). "TXNIP has been identified as a tumor suppressor gene and in cancer, a loss of TXNIP can lead to cell proliferation." (PMID 23520439, 2013). "However, its role appears to be tissue-specific, as some cancers, such as kidney or liver, exhibit higher TXNIP levels associated with poorer survival." (PMID 41213907, 2025). "The impaired TXNIP/TXN redox homeostasis might be associated with development of multiplex cancer especially of EVT in ESRD/ACRD kidney." (PMID 39020292, 2024). "A recently published article claimed that BC-derived sEVs promoted the activation of the Wnt pathway by cancer-associated fibroblasts (CAFs) through the miR-146a/Thioredoxin Interacting Protein (TXNIP) axis, which in turn enhanced BC cells invasion and metastasis." (PMID 36185265, 2022). "Suppression of TXNIP seems to be a promising strategy, while completely blocking the activity of TXNIP may cause disadvantageous effects, such as enhanced susceptibility to cancer and deteriorating the fasting response." (PMID 38789868, 2024). "TXNIP is a potent negative regulator of glucose uptake; in fact, its loss or downregulation is sufficient to increase glucose uptake, suggesting that low TXNIP levels may be a common route to aerobic glycolysis common in cancer." (PMID 33292639, 2020).
cancer (continued). "Consequently, due to the “historical” association between 1,25(OH)2D3 and TXNIP as a vitamin D upregulated protein, it has been suggested that 1,25(OH)2D3 could be used to reactivate TXNIP in cancers." (PMID 29534438, 2018). "Inhibiting BRD4 increased TXNIP levels and suppressed protein UFMylation, resulting in cancer cell cycle arrest and increased vulnerability to ferroptosis." (PMID 41249136, 2025). "Using data from the TCGA database, we found that TXNIP expression was downregulated in multiple tumors compared to that in corresponding normal tissues, suggesting that TXNIP can suppress cancer progression." (PMID 40008893, 2025). "In light of TXNIP’s antitumor function and frequent loss in human cancers, previous studies have explored various approaches to activating TXNIP expression in cancer cells." (PMID 40175348, 2025). "This inverse association between TXNIP and BRD4 expression was further corroborated through an analysis of the TCGA pan-cancer database." (PMID 41249136, 2025). "Across all scRNA-seq datasets available in TISCH (i.e. 78 datasets across 28 cancer types), TXNIP showed high expression levels in immune cells, fibroblasts and endothelial cells as well as malignant cells, irrespective of the cancer type." (PMID 40260243, 2025). "Our findings align with previous reports, such as the study showing that STARD7‐AS1 suppresses CC cell proliferation through the miR‐31‐5p/TXNIP axis, and another demonstrating miR‐27a‐3p's targeting of TXNIP in cancer." (PMID 40665897, 2025). "Future studies are needed to assess the involvement of the WWP1/TXNIP crosstalk in the regulation of leukemic cell sensitivity to anti‐cancer therapies." (PMID 39364720, 2025). "To evaluate the translatability of these in vitro findings to the clinic, we then explored TXNIP gene expression in cancer patients’ data." (PMID 40260243, 2025). "The NLRP3 inflammasome is involved in immune responses in various cancers, and numerous studies have highlighted the link between TXNIP and NLRP3 inflammasome activation." (PMID 40182050, 2025). "We first evaluated the expression of TXN, TXNRD1, and TXNIP in pan-cancer data from TCGA and GTEx to further investigate the connection between the Trx system and malignancies." (PMID 39744566, 2025). "In summary, we find that Dpep induces TXNIP in a cell context-dependent manner that in turn suppresses glucose uptake and glycolysis and contributes to apoptotic death of a range of cancer cells." (PMID 38920655, 2024). "TXNIP is a member of the arrestin family that plays complex biological roles, and can be either pro- or antitumorigenic in different types of cancers." (PMID 38396744, 2024). "Knockdown studies show that TXNIP significantly contributes to apoptotic death in those cancer cells in which it is induced by Dpep." (PMID 38920655, 2024). "By activating a specific thioredoxin interacting protein (TXNIP) and stabilizing the p27kip1 protein in the G1 phase (G1‐cell cycle arrest), d‐allose inhibits the development of cancer cells while sparing healthy cells." (PMID 39055230, 2024). "It is also noteworthy that metformin increases GDF15 and decreases TXNIP in cancer cells, an effect which has been suggested to contribute to metformin’s anticancer effects." (PMID 38255875, 2024). "TXNIP expression levels were markedly increased in both cell lines, suggesting that TXNIP gene expression plays a role in suppressing cancer cell growth." (PMID 39199548, 2024). "The cell-penetrating ATF5/CEBPB/CEBPD inhibitor peptide Dpep upregulates TXNIP mRNA and protein in the majority of cancer cell lines surveyed." (PMID 38920655, 2024). "ARRDC2, ARRDC4, and TXNIP share common association with certain neurodegenerative diseases, while ARRDC1 is implicated in cancer." (PMID 38270169, 2024). "In summary, our findings point to upregulated TXNIP as a context-dependent participant in cancer cell death evoked by Dpep." (PMID 38920655, 2024).
cancer (continued). "For instance, a study in TNBC identified that TXNIP suppression by MYC can reprogramme the metabolic phenotype of cancer cells." (PMID 37794178, 2023). "Numerous studies further demonstrated the key roles of c-Myc/TXNIP axis in regulation of various cancer cell survival." (PMID 37095099, 2023). "In cancers, the opposite has been observed, wherein TXNIP levels are lowered and SELENOM levels are higher." (PMID 38001759, 2023). "Accordingly, TXNIP can drive both beneficial and detrimental effects in different pathologies, like metabolic diseases and cancer." (PMID 37794178, 2023). "Papers that we consider to be key in understanding the role of TXNIP in cancer biology are highlighted in italic throughout the review." (PMID 37794178, 2023). "With important roles in several cancer types, TXNIP affects cell proliferation and death, drug sensitivity, angiogenesis, and glycolysis." (PMID 37794178, 2023). "TXNIP expression is often downregulated in cancer cells and the suppression of TXNIP expression in normal cells increases the risk of cancer." (PMID 37259304, 2023). "Previous studies have shown that restoration of TXNIP expression sensitizes cancer cells to cytotoxic chemotherapeutics." (PMID 36860653, 2023). "For these authors, the next steps in trying to understand the role of TXNIP in cancer, are to understand which functions of TXNIP are important in each different biological context." (PMID 37794178, 2023). "As such, the stage is now set for the field to assess the importance of thioredoxin binding in cancer models, and in so doing begin to decipher the impact of TXNIP’s diverse roles more specifically." (PMID 37794178, 2023). "TXNIP belongs to the α-arrestin family of proteins and its inappropriate regulation in cancer cells has been reported previously." (PMID 36860653, 2023). "Insulin-like growth factor 1, a growth factor known to promote cancer development, negatively regulates TXNIP expression enhancing its antiapoptotic effects." (PMID 37794178, 2023). "In this vein, a number of studies have shown that increased TXNIP expression can enhance the cytotoxicity of chemotherapeutic reagents by manipulating ROS levels, as the levels of ROS in cancer cells provide a potential therapeutic vulnerability." (PMID 37794178, 2023). "We presented evidence supporting the role of gnetin H as a glycolysis inhibitor and demonstrated that treatment of cancer cells with GH purified from peony seeds reduces the synthesis of lactic acid and the expression of TXNIP and is cytostatic." (PMID 37175448, 2023). "Vorinostat, a pan histone-deacetylase inhibitor, and rapamycin, an mTORC1 inhibitor, have been shown to limit disease progression in Ras-driven cancers, with the ability to induce TXNIP expression." (PMID 37794178, 2023). "We demonstrated that the treatment of cancer cells with GH purified from peony seeds is not only cytostatic but also simultaneously reduces the synthesis of lactic acid and the expression of TXNIP." (PMID 37175448, 2023). "In contrast, other reports show that high TXNIP levels can also correlate with poor clinical prognosis in some cancers." (PMID 37794178, 2023). "The main function of TXNIP is to induce apoptosis under oxidative stress and also to inhibit the proliferation and migration of cancer cells." (PMID 37156819, 2023). "For example, although crudely speaking most primary carcinomas express low levels of TXNIP, what is the key reason for this—metabolism, the inflammasome, angiogenesis, or immune crosstalk?" (PMID 37794178, 2023). "Currently, it is anticipated that TXNIP will be used as a molecular target for the treatment of various cancers." (PMID 36366411, 2022). "In a previous study we demonstrated that the inducible expression of the NAF-1 H114C mutant (with a high 2Fe-2S cluster stability) in cancer cells results in the enhanced expression of TXNIP that binds TRXs and induces oxidative stress and ferroptosis." (PMID 36009251, 2022).